HNRNPA2B1 (heterogeneous nuclear ribonucleoprotein A2/B1)
Diseases named in the same sentence as HNRNPA2B1 in open-access papers (continued):
Sharing a sentence is not in itself a finding about the gene and the disease.
cancer (continued). "Underscoring the functional relevance of these increases, increased expression of HNRNPA2B1 and PTBP1 has been shown to be responsible for the predominance of the PKM2 isoform that is the hallmark of many types of cancer, promoting the aerobic glycolysis that is important for cell growth." (PMID 20946641, 2010). "However, we did not detect any KRAS protein signal in the immunoprecipitated samples of Flag-hnRNPA2B1, implying that hnRNPA2B1 might carry distinct functional missions in different cancer species." (PMID 37716979, 2023). "HNRNPA2B1 may also be an independent prognostic factor and contribute to cancer progression." (PMID 35045837, 2022). "Whether HNRNPA2B1 plays a key role in various cancer types remains unclear." (PMID 35529270, 2022). "Thus, this study explored the possible oncogenic role of HNRNPA2B1, such as its expression levels, gene alteration, protein–protein interaction network, immune infiltration, and prognostic value in different cancer types using The Cancer Genome Atlas web platform." (PMID 35529270, 2022). "The translation initiation factor subunit EIF3D and the splicing factor HNRNPA2B1 can be independent prognostic factors which may contribute to retardation and promotion of cancer progression, respectively, through affecting cancer-related processes such as cell cycle." (PMID 33273988, 2020). "The results indicate that hnRNPA2B1 may provide a target for the treatment of a variety of cancers." (PMID 30755586, 2019). "DSS analysis observed that high expression of HNRNPA2B1 in nine cancers resulted in poor prognosis, including GBMLGG, LGG, LUAD, LUSC, LIHC, ACC, KICH, and low expression of HNRNPA2B1 in OV with poor prognosis." (PMID 39268079, 2024). "Some studies have reported the transcriptional and post-transcriptional regulation of hnRNPA2B1 in cancer, that c-Myc and BRCA1 promoted hnRNPA2B1 transcription, while activation of Fyn and Nm23-H1 stabilized hnRNPA2B1 protein expression." (PMID 37716979, 2023). "GEPIA, The Cancer Genome Atlas (TCGA) database, GSEA and western blot were used to detect the potential signaling pathways related to the roles of HNRNPA2B1 and NUF2 in OC cells." (PMID 36670423, 2023). "Heterogeneous nuclear ribonucleoprotein A2/B1 (HNRNPA2B1) is a protein that ubiquitously participates in RNA‐binding and pre‐RNA processing, regulating cancer cell metabolism, proliferation, migration, invasion, and apoptosis." (PMID 35441574, 2022). "Importantly, the effect of HNRNPA2B1 on pan-cancers may be connected with the cell cycle pathway." (PMID 35529270, 2022). "In the COSMIC database, 78, 114, 113, and 83 studies confirmed the correlation between HNRNPA2B1, BPTF, LRRK1, and PUM1 with cancer, respectively." (PMID 32300588, 2020). "We have identified a panel of six proteins viz., GOT1, HNRNPA2B1, MAPK1, PAK2, UBE2N, and YWHAB, which contribute to cancer development, and the transition of PCa from androgen dependent to independent stages." (PMID 32322560, 2020). "The results showed that the expression of HNRNPA2B1 was significantly positively correlated with the expressions of MKI67 and PCNA, which were the classic biomarkers of proliferative cancer cells." (PMID 33134163, 2020). "Among these cancer relapse-relevant genes, METTL16, FTO, EIF3D, and EIF3I were good prognostic factors, while TRA2A, HNRNPA2B1, and YTHDC2 were bad ones." (PMID 33273988, 2020). "Unsurprisingly, conforming to the manifestation of an oncogene, both the mRNA and protein levels of HNRNPA2B1 were closely related with EMT, which plays an important role in the invasion and metastasis of cancer cells." (PMID 28077929, 2017). "Recent studies have shown that heterogeneous nuclear ribonucleoproteins A2B1 (HNRNPA2B1), two structurally homologous proteins belonging to the hnRNP family, play important roles in normal development as well as in cancer processes in eukaryotic cells." (PMID 28077929, 2017).
cancer (continued). "Instead, we organize current evidence within a context-aware framework in which HNRNPA2B1 is discussed as a possible regulator of selected RNA fate modules rather than as an established pan-cancer RNA fate hub." (PMID 42292447, 2026). "HnRNPA2B1 and IGF2BP3, as m6A reader proteins, may play key roles in the progression of various cancers." (PMID 40770637, 2025). "Moreover, LINC01833 has been found to form a complex with heterogeneous nuclear ribonucleoprotein A2/B1 (HNRNPA2B1) in NSCLC, further highlighting its involvement in cancer progression." (PMID 40778107, 2025). "HNRNPA2B1 is an RNA binding protein involved in the transcription, splicing processing, transport, stability, telomere maintenance and DNA repair and its overexpression is reported to mediate EMT in different cancers." (PMID 37142981, 2023). "Moreover, by recruiting the microprocessor protein DGCR8, HNRNPA2B1 positively modulated the processing of pri-miR-93 via an m6A-depenent way and subsequently inhibiting its target gene FRMD6, a cancer suppressor gene." (PMID 37215455, 2023). "In addition, m6A‐recruited the binding proteins, YTHDC1, YTHDC2, YTHDF3, and FMR1 were inversely correlated, while HNRNPC, HNRNPA2B1, YTHDF1, and RBMX positively correlated TSs in most cancer types." (PMID 36239411, 2023). "In addition, G3BP2, WTAP, PCIF1, HNRNPA2B1, EIF3A, and IGF2BP2 were modulated in ≥three cancer types in uncertain manners." (PMID 35211628, 2022). "Notably, HNRNPA2B1 and HNRNPC showed extensive expression pattern in all cell types, but the expression of these m6A regulators was higher in M1 macrophages, GBM cancer cells, and T/NK cells." (PMID 35558067, 2022). "HNRNPA2B1, HNRNPC, LRPPRC, ALKBH5 showed high expression in almost all cancers." (PMID 35265626, 2022). "HNRNPA2B1 is also known to regulate the packaging of miRNA into endothelial cell EVs, although apparently without the involvement of the GGAG motif, and has been shown to be involved in the targeting of specific lncRNAs into cancer cell EVs." (PMID 35331218, 2022). "Both HNRNPA2B1 and HNRNPC might be cancer-promoting factors and potential prognostic biomarkers for LUAD." (PMID 36061307, 2022). "Besides that, HNRNPA2B1, YTHDC1, METTL14, WTAP, and ZC3H13 were downregulated in cancer tissues, whereas VIRMA had opposite alterations between these two databases." (PMID 33225598, 2021). "Furthermore, after network analysis, EPRS, HNRNPA2B1, BPTF, LRRK1, and PUM1 were demonstrated to have a broad correlation with cancers." (PMID 32300588, 2020). "Thus, we speculated that circDCP2 upregulates the CCND1 expression level by directly binding to HnRNPA2B1, thereby activating the PI3K-AKT pathway and promoting cancer progression." (PMID 40770637, 2025). "To date, there have been no pan-cancer studies of HNRNPA2B1, particularly within the TME." (PMID 39268079, 2024). "The positive pan-cancer correlations with m1A RNA methylation regulatory proteins YTHDF2 and ALKBH1, m5C methylation regulatory proteins DNMT1, DNMT3B, and ALYREF, and m6C RNA methylation regulatory proteins HNRNPC, HNRNPA2B1, and ELAVL1 were particularly significant." (PMID 36090896, 2022). "In addition, the copy number variations investigation revealed that HNRNPA2B1 gene showed widespread copy number amplification across various cancer types whereas almost no CNV was detected in LAML." (PMID 32915499, 2020). "In addition, the formation of the MIR100HG/hnRNPA2B1/TCF7L2 forward-regulatory loop and the c-MYC/LINC01234/hnRNPA2B1/miR-106b-5p/Cry2/c-MYc positive-feedback loop could effectively accelerate disease progression in cancer patients." (PMID 35879279, 2022). "In other cancer types, such as ESCA, GBM, KIRP, LAML, SARC, SKCM, TGCT, etc., HNRNPA2B1 expression also showed a negative correlation with immune infiltration." (PMID 39268079, 2024).
cancer (continued). "We observed the overexpression of isoforms of genes C3orf17, FRMD4A, FZD6, HNRNPA2B1, POSTN, PRKAA1, RRBP1 and VEGFA, and the under expression of TRIP12 isoform (ENST00000428959) in ACC patients who are not free of cancer, which is a surrogate for poor ACC outcomes." (PMID 33035235, 2020).
neurodegenerative disease (18 papers, 2014 to 2025). A disorder of the central nervous system characterized by gradual and progressive loss of neural tissue and neurologic function. "Heterogeneous nuclear ribonucleoprotein A2/B1 (hnRNPA2/B1) is an RNA-binding protein whose prion-like structure is prone to mutation and hence leads to neurodegenerative diseases, but its expression changes in PND remains unclear." (PMID 36337695, 2022). "In addition, several of the identified proteins had previously been linked to neurodegenerative diseases like hnRNPA1, hnRNPA2B1, Matrin3 and FMRP." (PMID 27164932, 2016). "Mutations in RBPs that affect SG biology, including FUS, TDP-43, hnRNPA1, hnRNPA2B1, and TIA1, underlie ALS, IBM, and other neurodegenerative diseases." (PMID 34291734, 2021). "The results suggested that FAM76B mediated neuroinflammation via influencing the translocation of hnRNPA2B1 in vivo during TBI repair and neurodegenerative diseases." (PMID 37643469, 2023). "Lastly, FAM76B was shown to interact with hnRNPA2B1 in human tissues taken from patients with acute, organizing, and chronic TBI, and with different neurodegenerative diseases." (PMID 37643469, 2023).
infection (13 papers, 2015 to 2025). The state of being infected such as from the introduction of a foreign agent such as serum, vaccine, antigenic substance or organism. "Next, to determine if HNRNPA2B1-deficient macrophages were defective for cell intrinsic control of Salmonella replication, we performed an ex vivo infection of macrophages." (PMID 40414614, 2025). "HNRNPA2B1-deficient mice succumbed to infection earlier than controls." (PMID 40414614, 2025). "hnRNPA2B1 (hereafter A2B1) has been identified as a novel DNA sensor for surveillance of infection from DNA viruses." (PMID 40689679, 2025). "Collectively our work demonstrates a key role for HNRNPA2B1 in mounting balanced inflammatory responses in macrophages ex vivo as well as in mouse models of endotoxic shock and infection." (PMID 40414614, 2025). "Cellular RBPs that are associated with SVA 5′-UTR were systematically examined, as well as those translocated to the cytoplasm after SVA infection, resulting in the identification of hnRNPA2B1 as a novel ITAF for SVA IRES-driven translation." (PMID 39207136, 2024). "Here, heterogeneous nuclear ribonucleoprotein A2B1 (hnRNPA2B1) was identified as a critical regulator of the translational landscape during SVA infection." (PMID 39207136, 2024). "In the present study, it was determined that hnRNPA2B1 undergoes a profound nucleocytoplasmic translocation upon SVA infection, which is in concordance with previous observations following EV71 infection." (PMID 39207136, 2024). "The increased accumulation of hnRNPA2B1 in the cytoplasm of infected cells was observed from approximately 6 hpi and continued to increase as the infection cycle progressed." (PMID 39207136, 2024). "Taken together, these results demonstrated that hnRNPA2B1 migrates from the nucleus to the cytoplasm following SVA infection." (PMID 39207136, 2024). "Furthermore, hnRNPA2B1 appears to be a conserved determinant of the translation and infection of IRES-containing picornaviruses and flaviviruses." (PMID 39207136, 2024). "Are the nucleic acid sensors such as SAFA or hnRNPA2B1 capable of sensing SFTSV infection?" (PMID 34122440, 2021). "It will be an interesting topic to investigate whether SAFA can be translocated to cytoplasm like hnRNPA2B1 under infection status." (PMID 34122440, 2021). "The two- to fourfold lower read-out/exon ratios observed for two of the four genes (FUS and HNRNPA2B1) in Δvhs infection resulted from higher total RNA levels compared with wild-type HSV-1 infection reflecting the lack of vhs activity rather than reduced read-out36." (PMID 25989971, 2015). "Likewise, during infection with the gram-negative bacterial pathogen Salmonella enterica, HNRNPA2B1-deficient mice fail to mount protective inflammatory responses and experience higher bacterial burdens." (PMID 40414614, 2025). "For instance, after infection with herpes simplex virus-1 (HSV-1), the m6A-binding protein Recombinant Mouse Heterogeneous nuclear ribonucleoproteins A2/B1 (hnRNPA2B1) recognizes viral DNA and undergoes homodimerization." (PMID 40867537, 2025). "As expected, hnRNPA2B1 was gradually redistributed from the nucleus to the cytoplasm in both PK-15 and IBRS-2 cells after SVA infection, especially at 6 and 8 hpi." (PMID 39207136, 2024). "Consistent with this, a significant reduction in the levels of total and negative-strand viral RNA was detected in hnRNPA2B1 knockdown cells 4–8 h after SVA infection." (PMID 39207136, 2024). "According to the relocalized MS data, the abundance of hnRNPA2B1 was consistently increased in the cytoplasm (abundance ratio of SVA:mock, 4) and decreased in the nucleus (abundance ratio of SVA:mock, 0.82) at 8 h post-infection (hpi)." (PMID 39207136, 2024). "Moreover, we have demonstrated that PAC5 binds hnRNPA2B1 being a new drug target for HBV and SARS-CoV-2 omicron infections." (PMID 36726760, 2023).
infection (continued). "In the absence of infection, hnRNPA2B1 interacts with the m6A demethylase FTO to remove m6A from hnRNPA2B1 targets and induce their nuclear retention." (PMID 35087521, 2021).
myopathy (5 papers, 2021 to 2023). A disease of the muscle in which the muscle fibers do not function properly. "Since the identification of the first HNRNPA2B1 MSP family, screening of MSP and large ALS patient cohorts has shown that HNRNPA2B1 variants are a rare cause of sporadic and familial motor neuron disease; however, its potential role in myopathies has remained unclear." (PMID 35484142, 2022).
neuromuscular disease (2 papers, 2022 to 2023). "By combining machine learning with RBP engagement scoring, we discovered that the neuromuscular disease-associated RBP Hnrnpa2b1 is a differentiation-specifying regulator of myogenesis that controls myogenic cell fate transitions during terminal differentiation in mice." (PMID 35695839, 2022). "Single-cell RNA sequencing of regenerated skeletal muscle showed that neuromuscular diseases were related to HNRNPA2B1, and HNRNPA2B1 controlled the fate transformation of myogenic cells during terminal differentiation." (PMID 37048101, 2023).
infectious disease (1 paper, 2023). A disorder directly resulting from the presence and activity of a microbial, viral, or parasitic agent in humans. "Our results indicate that PAC5 is a novel small-molecule agonist of hnRNPA2B1, which may have a role in dealing with emerging infectious diseases now and in the future." (PMID 36726760, 2023).
HNRNPA2B1 also shares sentences with these, for which no sentence is quoted: cognitive decline (3 papers); colon adenocarcinoma (3); spinal muscular atrophy (3); systemic lupus erythematosus (3); asthma (2); cognitive deficits (2); endometrial cancer (2); inclusion body myositis (2); mixed connective tissue disease (2); Paget's disease of bone (2); Parkinson disease (2); postpartum depression (2); pulmonary hypertension (2); rectum adenocarcinoma (2); renal cell carcinoma (2); stomach adenocarcinoma (2); thyroid cancer (2); Addison’s disease (1); adenocarcinoma (1); Amyotrophic lateral sclerosis/frontotemporal dementia (1); androgen alopecia (1); Autoimmunity (1); bladder tumors (1); breast invasive carcinoma (1); cholangiocarcinoma (1); congenital myasthenic syndrome (1); corticobasal degeneration (1); diffuse large B-cell lymphoma (1); distal myopathy (1); Down syndrome (1).
A further 42 diseases each share a sentence with HNRNPA2B1 in 1 paper.